TP73 (tumor protein p73)
Diseases named in the same sentence as TP73 in open-access papers (continued):
Sharing a sentence is not in itself a finding about the gene and the disease.
cervical carcinoma (continued). "Moreover, a microdissection assay was performed in cervical cancer tissues and adjacent normal tissues, and showed high levels of TP73 in cervical cancer tissues." (PMID 31332036, 2019). "Notably, all eight genes that were frequently methylated in the HPV-transfected cell lines and cervical cancer cell lines (i.e. TP73, ESR1, RARβ, DAPK1, MGMT, CADM1, CDH13 and CHFR) overlapped with those found to be methylated in the cervical carcinoma specimens." (PMID 17971771, 2007). "The experimental results confirm that ATG4D, CD46, TP73 and HSPB8 are decreased in cervical cancer, and the prognosis model shows a negative correlation with the risk score, it could be inferred that they had a protective effect on the occurrence and prognosis of cervical cancer." (PMID 34238288, 2021). "Finally, among the 12 autophagy biomarkers related to the survival of cervical cancer, based on literature search, we selected 6 genes (ATG4C, ATG4D, CD46, TP73, SERPINA1 and HSPB8) to verify their RNA expression in CC and normal cervical tissue samples." (PMID 34238288, 2021). "Relationships between TP73 expression and clinicopathologic features have not been reported in cervical cancer patients." (PMID 31332036, 2019). "The statistical result suggested that there was significant difference in TP73 expression between cervical cancer tissues compared with normal cervical epithelium tissues (P<0.001), which was consistent with the results of TCGA database." (PMID 31332036, 2019). "TP73 was found high expression in cervical cancer cases, however it is not reported for gastric cancer in literature." (PMID 30212456, 2018). "Owing to the lack of reports on the correlation between TP73 protein expression and clinicopathologic features of cervical cancer, the aim of our research was to explore the clinical and prognostic significance of TP73 protein expression in cervical cancer patients." (PMID 31332036, 2019).
lung carcinoma (11 papers, 2011 to 2024). "Strikingly, expression of some of the lung cancer-related genes were dysregulated in immune cells of smokers, such as TP73 which was decreased in mast cells." (PMID 32727470, 2020). "Other researchers studied the role of TP73 gene conducted in lung cancer." (PMID 35073920, 2022). "And the interaction of ITGB4 promoter with some transcription factors in other disease is also reported, such as KLF4 in glioma 21, RUNX1 in myeloid leukemia 22, ZEB1 in prostate cancer 23, TP73 in lung cancer 24, GLI1 in ovarian cancer 25, and JUN in pancreatic cancer." (PMID 31602273, 2019).
prostate carcinoma (10 papers, 2013 to 2025). A carcinoma that arises from epithelial cells of the prostate gland. "Another gene, TP73 were extensively investigated in prostate cancer." (PMID 35053153, 2021). "We previously reported a significant role of genetic variation in TP73 in prostate cancer." (PMID 35053153, 2021). "TP73 and WT1, which were also misregulated upon PLAGL1 knockdown, were previously found to be highly methylated in prostate cancer, along with PLAGL1." (PMID 33171905, 2020). "The overexpression of CXCL3 and its receptor CXCR2 promoted the proliferation and migration of cancer cells by regulating the expression of genes, including ERK, BAX, TP73, and NDRG3, which enhance the oncogenic potential of prostate cancer." (PMID 30686982, 2018). "Our results suggest an overall tendency towards disruption of methylation at imprinted loci in prostate cancer tissue, and our data provide the first suggestion of disrupted imprinting patterns in cancer for four imprinted genes (DLK1, PLAGL1, SLC22A18, and TP73)." (PMID 23890537, 2013).
ovarian carcinoma (9 papers, 2012 to 2025). A malignant neoplasm originating from the surface ovarian epithelium. "Taken together, the data at the protein and transcriptional level provide evidence that TP73 is frequently overexpressed in ovarian cancer and is associated with an aggressive platinum-resistant phenotype." (PMID 40244040, 2025). "Thus, it is interesting to study the association between TP73 and platinum resistance in ovarian cancer." (PMID 34858477, 2021). "Most studies have shown that positive immunohistochemical staining TP73 was associated with worse clinical outcome in extrahepatic bile duct carcinoma, cholangiocellular carcinoma, hepatocellular carcinoma, colorectal cancer, ovarian cancer and esophageal squamous cell carcinoma." (PMID 31332036, 2019). "In ovarian cancer cell lines, the downregulation of TP73 transcripts by epigenetic silencing has been reported." (PMID 40244040, 2025). "The tumor-promoting role of TP73 in ovarian cancer was also reported in two other studies, and high expression of this gene was associated with advanced ovarian carcinoma when compared with the early-stage and borderline ovarian tumors." (PMID 35867729, 2022). "However, there was no statistical association between TP73 expression and clinicopathologic features in hepatocellular carcinoma, colorectal cancer and ovarian cancer." (PMID 31332036, 2019).
gastric cancer (8 papers, 2011 to 2025). A primary or metastatic malignant neoplasm involving the stomach. "First, the database was assessed to select the stomach tissue, gastric cancer cell lines, and TP73 from associated genes." (PMID 40181843, 2025). "This study adopted a case–control design to explore alleles and TP73 gene rs1801173 genotypes in GC patients and explore the role of TP73 genetic status and on risk of gastric cancer." (PMID 35073920, 2022). "Based on the background above, this study examined rs1801173 locus polymorphism of TP73 gene in patients with gastric cancer cases and healthy subjects." (PMID 35073920, 2022). "This study investigated the role of TP73 gene polymorphism, rs1801173on risk of gastric cancer." (PMID 35073920, 2022). "In Epstein-Barr virus-associated gastric cancer (EBVaGCs), TP73 methylation is detected in 92%–100% of cases, compared to just 5% in EBV-negative gastric cancer." (PMID 38933923, 2024). "miR647 modulates FBLN1, FN1, and MST1R genes and has a tumor-promoting role in gastric cancer via repression of TP73." (PMID 34357026, 2021). "TP73 gene rs1801173 polymorphism is not significantly correlated with susceptibility of gastric cancer." (PMID 35073920, 2022). "As a result, the findings may have limitations that preclude conclusively ruling out an correlation between TP73 gene and gastric cancer." (PMID 35073920, 2022). "TP73 gene rs1801173 polymorphism was not significantly correlated with risk of gastric cancer." (PMID 35073920, 2022).
lymphoma (8 papers, 2011 to 2023). A malignant (clonal) proliferation of B- lymphocytes or T- lymphocytes which involves the lymph nodes, bone marrow and/or extranodal sites. "It is possible that in the Eμ-Myc mouse lymphoma cells, TP73 was activated to induce the expression of the pro-apoptotic proteins BIM, PUMA and NOXA to thereby induce apoptosis." (PMID 36739334, 2023). "Previously, TP73 was proved to be an independent survival indicator in some cancers, such as lymphomas, leukemia, and gliomas." (PMID 35756491, 2022). "For example, TP73 has been found to be transcriptionally silenced in lymphoblastic leukemias and lymphomas induced by CpG island methylation." (PMID 30913233, 2019). "Furthermore, TP73 deletion has been shown to impact lymphoma formation by several mechanisms, such as altered gene expression patterns, defective early T-cell growth, impaired apoptosis, and chromosomal abnormality accumulation." (PMID 36033519, 2022). "While inputting lymphoma into TMREC and ranking the results, a cascade named TP73 → miR-145 → MYC → miR-15a → MYB → miR-155 → SPI1 → miR-338 with the highest score was obtained." (PMID 25932650, 2015).
colorectal cancer (7 papers, 2011 to 2024). A primary or metastatic malignant neoplasm that affects the colon or rectum. "Altered TP73 expression is observed in most human cancers and is associated with adverse outcomes in colorectal cancer patients." (PMID 38933923, 2024). "Studies on colorectal cancer have found that TP73-positive tumor patients have a greater malignancy risk and shorter survival." (PMID 38933923, 2024). "Polymorphism and expression of TP73 were associated with carcinogenesis and colorectal carcinoma development." (PMID 29228695, 2017). "Kotulak and colleagues support this finding as they suggest that TP73 may play a role as a tumor suppressor in colorectal cancer progression." (PMID 38051091, 2024).
esophageal cancer (7 papers, 2017 to 2023). A primary or metastatic malignant neoplasm involving the esophagus. "For TP73, a study showed that a SNP (rs2273953) in TP73 in esophageal cancer patients impacted disease-free survival." (PMID 34712617, 2021). "For example, PAX9 and TP73 appeared specifically in esophagus cancer." (PMID 34712617, 2021). "GSVA found that Tumor microenvironment, Epithelial cells, as well as Barrett's esophagus and esophagus cancer were significantly up-regulated in the high NCS group, while TP73 and TP63 targets, Response to metal ions, Response to THC were significantly downregulated." (PMID 37291676, 2023).
hepatocellular carcinoma (7 papers, 2011 to 2024). A malignant tumor that arises from hepatocytes. "Two target genes of E2F4, CDK1 and TP73 were also involved in liver cancer development and proposed as prognostic marker of poor patient survival prognosis in hepatocellular carcinoma." (PMID 28347313, 2017). "TP73 plays an important role in the development of malignant glioma and hepatocellular carcinoma." (PMID 35538551, 2022). "Moreover, upregulation of cancer-specific isoforms of TP73, CDH17, KLF6, FGFr2, FGFR3, DNMT3b3, and OPN has been reported in human hepatocellular carcinoma (HCC) and promoted cell cycle progression, proliferation, invasion and metastasis." (PMID 35463320, 2022).
melanoma (7 papers, 2017 to 2024). A malignant, usually aggressive tumor composed of atypical, neoplastic melanocytes. "We use the paradigm of melanoma transition from less invasive to highly aggressive stages in order to show that major players of metastasis, such as TP73 gene products, are implicated in this process." (PMID 33339112, 2020). "We found that all examined MAPKi-resistant melanoma cell lines exhibit a significantly lower basal expression of the TAp73 isoforms (TA TP73) in comparison to the corresponding MAPKi-sensitive cells." (PMID 30206212, 2018).
glioma (6 papers, 2006 to 2024). A benign or malignant brain and spinal cord tumor that arises from glial cells (astrocytes, oligodendrocytes, ependymal cells). "In gliomas, increased TP73 served as a stand-alone high-risk factor affecting the prognosis, while the downregulation of TP73 was closely related to favorable OS outcome." (PMID 35756491, 2022). "After that, integrated with the four datasets containing WHO grade II/III glioma cases, we further verified the credibility of TP73 acted as an independent prognostic risk factor for grade II/III glioma." (PMID 34121368, 2021). "Cox regression analysis indicated that high expression of TP73 shared an independent high‐risk factor impacting the prognosis of WHO grade II/III glioma." (PMID 34121368, 2021). "So far, few studies focus on the association of TP73 alteration and prognosis significance of glioma, the correlation between TP73 expression and 1p/19q codeletion, their integrated prognostic significance in WHO grade II/III glioma, additionally." (PMID 34121368, 2021). "It was proposed that high TP73 expression can be a high‐risk factor for evaluating the survival outcome of patients diagnosed with WHO grade II/III glioma." (PMID 34121368, 2021). "Hence, we are confident that high expression of TP73 is an independent high‐risk factor impacting the prognosis of WHO grade II/III glioma." (PMID 34121368, 2021). "Our analysis found that TP73 alternation can be a risk factor in WHO grade II/III glioma." (PMID 34121368, 2021). "In contrast, TP73 profile is more valuable for evaluating the prognosis of IDH‐wildtype glioma patients (such patients always share 1p/19q intact)." (PMID 34121368, 2021). "In summary, TP73 expression has remarkable significance for the prognostic evaluation of WHO grade II/III glioma, especially for IDH‐mutant subtype WHO grade II/III glioma." (PMID 34121368, 2021). "In this study, we first explored the correlation between TP73 mRNA expression and glioma classification; and analyzed the prognostic significance of TP73 mRNA expression and DNA methylation." (PMID 34121368, 2021). "We found that TP73 was differentially expressed in different types of glioma from the public databases of glioma." (PMID 34121368, 2021). "Meanwhile, TP73 mRNA expression profile and its prognostic prediction capacity were verified by a cohort of glioma specimens." (PMID 34121368, 2021). "Integrating with four independent glioma datasets, subsequent Meta‐analysis verified that low expression of TP73 was closely related to favorable OS, especially in IDH‐mutant subtype." (PMID 34121368, 2021). "We found that TP73 mRNA was lower expressed in normal cerebral tissues, and TP73 expression was positively correlated with the grade of glioma, strikingly (p < 0.0001)." (PMID 34121368, 2021). "We implemented χ2 test to analyze the correlation between 3 subtypes of glioma molecular classification and TP73 expression in 3 datasets of CCGA database." (PMID 34121368, 2021). "The expression of TP73 were strongly correlated with glioma molecular classification of WHO grade II/III glioma in CGGA_325, CGGA_693 and CGGA_301 datasets (p < 0.0001; p = 0.0003; p = 0.0369, respectively)." (PMID 34121368, 2021). "The results indicated that the expression level of TP73 was positively correlated with the grade of glioma, and the high‐expression subgroup suffered a worse prognosis, which was consistent with previous analytical results." (PMID 34121368, 2021). "In summary, our funding supports that TP73 gene can perform as a reliable biomarker to evaluate the survival outcome of patients diagnosed with WHO grade II/III glioma." (PMID 34121368, 2021).
glioma (continued). "In conclusion, we systematically analyzed the phenotypic characteristics of TP73 in WHO grade II/III glioma, and its correlation with survival time and clinical phenotypes (especially with molecular classification and tumor grade) through multi‐datasets." (PMID 34121368, 2021). "Second, the mechanism of TP73 and its isoforms contribute to the pathogenesis and progression of glioma is still poorly understood." (PMID 34121368, 2021). "TP73 mRNA expression and DNA methylation profile can be a risk factor impacting the prognosis of WHO grade II/III glioma independently, or combining with current glioma molecular classification." (PMID 34121368, 2021). "The results indicated that the expression level of TP73 was positively correlated with the grade of glioma (p = 0.0435), and the highest expressed in GBM subgroup." (PMID 34121368, 2021). "Up until now, the status of the Tp73 gene involving its various isoforms has been examined in ovarian tumours, hepatocarcinomas, vulval cancers, oesophagus and gliomas (this report)." (PMID 17047653, 2006). "Another aspect is the differential expression of Tp73 transcripts in the peripheral and central areas of low-grade tumours as compared to high-grade gliomas that overexpress the gene in both areas." (PMID 17047653, 2006). "Expression levels of P1 promoter generated Tp73 isoforms – and particularly ΔEx2–3 – indeed allow for prediction of the clinical progression of low-grade gliomas in adults." (PMID 17047653, 2006). "Finally, to better insight the functional role of TP73 gene in the occurrence and progression of glioma, we exploited the LGG dataset of TCGA database." (PMID 34121368, 2021). "Finally, we preliminarily predicted the possible functional mechanism of aberrant TP73 in glioma via TP73‐related differential mRNA in grade II/III glioma." (PMID 34121368, 2021). "Therefore, it is necessary to synthesize the TP73 mRNA expression and DNA methylation level when studying the biological role of TP73 in glioma and its prognostic significance." (PMID 34121368, 2021). "The analysis found that TP73 expression was positively correlated with the grade of glioma, and showed a strong correlation with glioma molecular classification, which revealed significantly higher TP73 expression in IDH‐wildtype than in IDH‐mutant subtype of WHO grade II/III glioma." (PMID 34121368, 2021). "Moreover, we utilized a combination of 1p/19q codeletion status and TP73 expression level to analyze the prognosis of WHO grade II/III glioma." (PMID 34121368, 2021). "Those inspired us to disclose the role of TP73 participation in the pathogenesis of glioma." (PMID 34121368, 2021). "Finally, TP73 expression of 53 glioma specimens was measured by qRT‐PCR, which was consistent with the previous analytical result, and TP73 high‐expression subgroup suffered worse PFS than TP73 low‐expression subgroup." (PMID 34121368, 2021). "We aim to analyze the correlation between TP73 mRNA expression, DNA methylated alteration and the prognosis of WHO grade II/III glioma, utilizing bioinformatics to evaluate its significance as a risk‐factor in predicting the prognosis of these glioma patients." (PMID 34121368, 2021). "Conversely, the favorable prognostic outcome of 1p/19q codeletion glioma may essentially, partly due to the low expression of TP73." (PMID 34121368, 2021).